ALDH1A1 (aldehyde dehydrogenase 1 family member A1)
Diseases named in the same sentence as ALDH1A1 in open-access papers (continued):
Sharing a sentence is not in itself a finding about the gene and the disease.
ovarian carcinoma (continued). "CM37, another small molecule ALDH1A1 inhibitor, reduced spheroid formation in ovarian cancer cell lines OVCAR8 and OVCAR3 at 5 and 20 μM, respectively; however, an IC50 has yet to be determined." (PMID 38612911, 2024). "We performed an FACS analysis of the commonly used stem cell markers in ovarian cancer (ALDH1A1 and CD44)." (PMID 36375842, 2023). "Platinum induced senescence and cancer stemness in ovarian cancer cells by enhancing aldehyde dehydrogenase 1A1 (ALDH1A1) activity." (PMID 36834846, 2023). "The impact of ALDH1A1 expression on treatment resistance was initially observed in taxane- and platinum-resistant ovarian cancer cells." (PMID 38201468, 2023). "The upregulation of POLQ/Polθ by ALDH1A1 is further confirmed in another ovarian cancer cell line Kuramochi." (PMID 37429899, 2023). "Overexpression of ALDH1A1 is able to enhance DNA repair and render ovarian cancer cells resistant to olaparib treatment." (PMID 37429899, 2023). "It was reported that ovarian cancer can also be prognosticated poorly based on high ALDH1A1 expression in the immunohistochemistry of the ovarian tissue." (PMID 36768291, 2023). "Our previous study has revealed that PARPi treatment can induce the expression of ALDH1A1, which renders ovarian cancer cells resistant to PARPi by enhancing MMEJ12." (PMID 37429899, 2023). "As already proven in our previous research and by others, the ALDH1A1-positive populations of ovarian cancer cells were more resistant to chemotherapeutic drugs used in the standard treatment of ovarian cancer patients." (PMID 36768723, 2023). "The result of this analysis indicated ALDH1A1 expression in tumors as an independent prognostic factor of shorter overall survival and progression-free survival in patients with epithelial ovarian cancer." (PMID 36768723, 2023). "A broad analysis of multiple ovarian cancer cell lines revealed significantly higher ALDH1A1 gene expression in taxane- and platinum-resistant cell lines." (PMID 37628927, 2023). "From complementary DNA microarray data, ALDH1A1 was downregulated in human ovarian cancer cell line cells, and hypermethylation of ALDH1A2 was higher in the cancer cell lines than in immortalised human ovarian epithelial cell lines." (PMID 36768694, 2023). "Here, we find that ALDH1A1 enhances the expression of DNA polymerase θ (Polθ, encoded by the POLQ gene) in ovarian cancer cells." (PMID 37429899, 2023). "Using compound 974 to target ovarian cancer stem cells, we show that ALDH1A1 plays a key role in cancer stemness." (PMID 35884498, 2022). "We describe the discovery of a novel ALDH1A1 inhibitor called 974 and show that targeting ALDH1A1 with 974 decreases the population of ovarian cancer stem cells." (PMID 35884498, 2022). "Collectively, these data demonstrate that ALDH1A1 is essential for the maintenance of stemness in ovarian cancer cells and that 974 significantly inhibits stemness phenotypes." (PMID 35884498, 2022). "Even though ALDH1A3 expression is elevated in primary ovarian cancer, high ALDH1A1 in tumors is correlated with a poor prognosis in patients, suggesting that ALDH1A1 is the more important target for improved survival." (PMID 35884498, 2022). "In our study, the drug-resistant ovarian cancer cell lines revealed a strong expression of drug transporters, the presence of ALDH1A1+ population, and expression of many ECM molecules, especially collagens." (PMID 35328460, 2022). "Accordingly, the ALDH1A1 inhibitor NCT-501 synergized with Olaparib in cell culture and xenograft models of BRCA2-mutated ovarian cancer." (PMID 35205643, 2022). "Similar results were observed using combined ALDH and ATM/ATR inhibitors in HR-proficient ovarian cancer cells, substantiating ALDH1A1 and related enzymes as a potential target for therapy." (PMID 35205643, 2022).
ovarian carcinoma (continued). "We demonstrated that 974 inhibited stemness phenotypes in ovarian cancer cell lines expressing ALDH1A1, and an in vivo limiting dilution analysis demonstrated an essential role for ALDH1A1 in CSC survival." (PMID 35884498, 2022). "Ovarian cancer cells with increased ALDH1A1 expression have a higher self-renewal ability, and HGSOC patients with tumors expressing high ALDH1A1 have poor overall survival." (PMID 35884498, 2022). "Targeting ALDH1A1 using small-molecule inhibitors in combination with chemotherapy therefore presents a promising strategy to prevent ovarian cancer recurrence and has the potential for clinical translation." (PMID 35884498, 2022). "Protecting the metabolically labile aldehyde from oxidation maintained ALDH1A1 specificity, producing positive tumour-to-background images in mouse models of ovarian cancer." (PMID 35656483, 2022). "The presence of ALDH1A1+ cells was observed both in vivo in ovarian cancer patients and in vitro in drug-resistant OC cell lines." (PMID 35328460, 2022). "Because platinum-based chemotherapy has been shown to enhance SASP and subsequently stemness in ovarian cancer, we investigated the effect of ALDH1A1 inhibition on senescence in cisplatin (CDDP)-treated cells." (PMID 35884498, 2022). "Landen and colleagues first identified ALDH1A1+ cells possessing CSC phenotype in ovarian cancer cell lines." (PMID 35448203, 2022). "Ovarian cancer stem cells have a high expression of ALDH1A1, and patients with a high level of ALDH1A1 in their tumor have worse survival." (PMID 35884498, 2022). "This study aimed to investigate the significance of ALDH1A1+ cells in the maintenance of drug resistance in ovarian cancer cell lines and the biological effects of ALDH1A1 gene knockout." (PMID 35328460, 2022). "In brief, in ovarian cancer cells, Olaparib increased ALDH1A1 expression through the BET protein BRD4, thereby activating alternate DNA repair pathways in cells harboring a BRCA2 mutation." (PMID 35205643, 2022). "One of the universal markers of CSCs among solid tumors is the expression of ALDH1A1, and the presence of ALDH1A1 cells correlated with ovarian cancer progression and drug resistance." (PMID 33921897, 2021). "According to the CSCs model and our results, ALDH1A1-positive cancer cells can be responsible for drug resistance development in ovarian cancer." (PMID 33921897, 2021). "Accumulating evidence suggests that ALDH1A1 regulates the maintenance of ovarian CSCs, ALDH+ ovarian cancer cells exhibit stem cell-like properties, and knock-down of ALDH1A1 in ovarian cancer cells diminishes clonogenic ability." (PMID 34064635, 2021). "Inhibition of BRD4 by BET inhibitors suppresses ALDH1 activity by targeting ALDH1A1 superenhancer in ovarian cancer." (PMID 32175692, 2020). "Treatment with CM37, a small molecule with inhibitory activity against ALDH1A1, suppressed spheroid proliferation of ovarian cancer cells and reduced expression of OCT4 and SOX2 in ALDH+ cells in ascites and ovarian cancer cell lines." (PMID 35582216, 2020). "Previously, we described increased expression of LOX in PAC and TOP resistant ovarian cancer cell lines, and its expression was upregulated in ALDH1A1 positive cells." (PMID 32283808, 2020). "Previously, we observed the subpopulation of ALDH1A1 positive CSCs in ovarian cancer cell lines resistant to PAC and TOP." (PMID 31027318, 2019). "Here we describe the activity of CM37, a new specific and potent small molecule inhibitor for ALDH1A1 in ovarian cancer models enriched in cells with stemness characteristics." (PMID 30965686, 2019). "This was the case when two separate labs knocked down ALDH1A1 with shRNA in ovarian cancer cell lines or patient-derived ovarian cancer spheroids, showing that ALDH1A1 decreases and increases proliferation." (PMID 31075118, 2019). "DDB2 also represses ovarian cancer cell dedifferentiation by inhibiting the transcription of aldehyde dehydrogenase 1 family member A1 (ALDH1A1)." (PMID 31635251, 2019).
ovarian carcinoma (continued). "CSCs, described as ALDH1A1-positive populations, were described also in ovarian cancer in vivo, and in OC drug-resistant cell lines." (PMID 31412536, 2019). "Here, we describe in further detail the effects of this selective inhibitor in ovarian cancer models and the significance of the ALDH1A1 enzyme to the ovarian cancer stemness phenotype." (PMID 30965686, 2019). "ALDH1A1 expression correlated with drug resistance and tumor progression in breast cancer and ovarian cancer among others." (PMID 31027318, 2019). "In ovarian cancer, aldehyde dehydrogenase (ALDH) activity due to ALDH1A1 gene expression has been associated with stemness and drug resistance." (PMID 30841549, 2019). "Ovarian cancer patients with high ALDH1A1 expression displayed a diminished response to platinum-based chemotherapy." (PMID 30166520, 2018). "Taken together, our data clearly demonstrate that enhanced ALDH1A1 expression plays a crucial role in DDB2 silencing-promoted ovarian cancer cell dedifferentiation." (PMID 29752431, 2018). "In this report we have studied the expression of LOX, collagens, and ALDH1A1 in drug-resistant ovarian cancer cell lines." (PMID 30583585, 2018). "These authors have also compared the expression of aldehyde dehydrogenase 1A1 (Aldh1A1), a marker for ovarian cancer stem cells, between primary and relapse tumor samples and have found an inverse relationship between Aldh1A1 and DRP1 expression." (PMID 29466320, 2018). "As a consequence, the transcription of the ALDH1A1 gene is repressed in ovarian cancer cells possessing high levels of DDB2." (PMID 29752431, 2018). "Previously we have described a TOP-resistant ovarian cancer cell line showing high expression of the drug transporter BCRP along with the subpopulation of ALDH1A1-positive cells." (PMID 30583585, 2018). "ATRA reduced ALDH1A1 levels and inhibited sphere formation and invasion in ALDH1-high cisplatin-resistant ovarian cancer cells." (PMID 30166520, 2018). "Knockdown of ALDH1A1 in ovarian cancer cell line A2780 decreases regulators KLF4 and p21, which are the cell cycle checkpoints, and leads to an enhanced cell proliferation." (PMID 29552329, 2018). "Such role was confirmed by the finding that the knockdown of ALDH1A1 gene in ovarian cancer cell lines can restore the ovarian cancer cells’ sensitivity to chemotherapy in vitro and xenograft models in mouse." (PMID 29552329, 2018). "Regulation of ALDH1A1 in ovarian cancer stem cells is suggested at the transcriptional level through Wnt/β-catenin pathway." (PMID 29552329, 2018). "To this end, we knocked down the expression of DDB2 and ALDH1A1 either separately or simultaneously in the 2008 ovarian cancer cell line, and analyzed the change of CSC abundance phenotypically and functionally." (PMID 29752431, 2018). "Sato et.al showed that ovarian epithelial cancer cells and tumors express high levels of ALDH1A1 compared with normal cells, suggesting ALDH1A1 as a potential biomarker for CSCs." (PMID 28404917, 2017). "Because secreted IL-6 contributes to chemoresistant cancer stem cells by inducing aldehyde dehydrogenase (ALDH1A1) we performed a survival assay with conditioned media (CM) from ovarian cancer cells treated for 24 hours with either PNA3 or control PNA." (PMID 28420874, 2017). "We show ALDH1A1(+) ovarian cancer cells display increased HOTAIR expression and PNA3 treatment decreases ALDH1A1 level in vitro and in vivo." (PMID 28420874, 2017). "We have previously demonstrated that transient repression of Drp1 elevates levels of Aldh1A1 in ovarian cancer cells (and other stem cell genes in other lineages)." (PMID 27509055, 2016). "Several of the characteristic CSC markers for ovarian cancer have been identified, among which high levels of ALDH1A1 are correlated with the sphere formation." (PMID 27863439, 2016). "For instance, aldehyde dehydrogenase 1 family member A1 (ALDH1A1) ALDH1A1 has been exploited to define CSC subpopulations in ovarian cancer." (PMID 27863439, 2016).
ovarian carcinoma (continued). "Our data supports an ALDH1A1-mediated platinum resistance mechanism in ovarian cancer via an altered regulation of cell cycle checkpoint and DNA repair network signaling." (PMID 25216266, 2014). "Further systematic evaluation of ALDH1A1/cell cycle axis is needed to confirm the platinum resistance and poor prognosis of ALDH1A1 positive ovarian cancers." (PMID 25216266, 2014). "Together our data indicates a connection between ALDH1A1 status to stemness and platinum resistance of ovarian cancer cells by altered regulation of DNA repair works." (PMID 25216266, 2014). "To further evaluate the role of ALDH1A1 in maintenance of cancer stem-like cells properties of platinum resistant ovarian cancer cells, we have downregulated ALDH1A1 specific isozyme using shRNAs." (PMID 25216266, 2014). "Together, these data suggests that ALDH1A1 status is one of the critical factors in maintaining stem-like cell properties and platinum resistance in ovarian cancer." (PMID 25216266, 2014). "In this study, we further investigated the potential role of ALDH1A1 isozyme in maintenance of ovarian cancer stem-like cells’ properties." (PMID 25216266, 2014). "Multiple ovarian cancer cell lines have been studied in a recent analysis, and in taxane and platinum resistant cell lines; in this study the ALDH1A1 expression and activity were found to be significantly higher." (PMID 23902592, 2013). "In an in vivo orthotopic mouse model of ovarian cancer, ALDH1A1 silencing using nanoliposomal siRNA sensitized both taxane- and platinum-resistant cell lines to chemotherapy, significantly reducing tumor growth in mice,compared to chemotherapy alone." (PMID 23902592, 2013). "Among patients, 72.9% of ovarian cancers had ALDH1A1 expression and the percent of ALDH1A1-positive cells correlated negatively with PFS." (PMID 23902592, 2013). "Our results are consistent with studies using gene expression microarrays which showed that the ALDH1A1 gene was down-regulated in malignant ovarian tumors compared to benign ovarian tumors or to normal ovary." (PMID 21176222, 2010). "Expression of ALDH1A1 was shown to be up-regulated in the highly malignant ovarian cancer cell line, TOV-112D compared to the low malignant TOV-81D." (PMID 19216797, 2009). "The expression of ALDH1A1 was also decreased in ovarian cancer tissues." (PMID 41383473, 2025). "Consequently, ALDH1A1 targeting can be important in an anticancer treatment, e.g., in acute myeloid leukemia, ovarian cancer, and triple-negative breast cancer." (PMID 39682629, 2024). "Based on these results, ALDH1A1 expression in tumors should be considered an independent prognostic factor of shorter overall survival and progression-free survival in patients with epithelial ovarian cancer." (PMID 36768723, 2023). "We have previously demonstrated that ALDH1A1 enhances MMEJ in ovarian cancer cells." (PMID 37429899, 2023). "In addition, HDAC inhibitors increased ALDH1A1 expression through the transcription factor BRD4 in ovarian cancer cells." (PMID 37954205, 2023). "Furthermore, we also demonstrated that the ALDH1A1-RA-Polθ axis plays a critical role in PARPi resistance in ovarian cancer cells." (PMID 37429899, 2023). "In fact, ALDH1A1 inhibition does sensitize colon, breast, pancreas, and ovarian cancer cells to chemotherapy, but further evidence is needed to conclusively determine whether this is also the case in AML." (PMID 37761947, 2023). "As ALDH1A1 is also a cancer stem cell marker in ovarian cancer, I examined whether acquisition of paclitaxel resistance is accompanied by development of the cancer stem cell phenotype." (PMID 36139693, 2022). "Collectively, our data demonstrate that targeting ALDH1A1 in cancer stem cells could be an effective strategy to overcome chemotherapy resistance in ovarian cancer." (PMID 35884498, 2022). "ALDH1A1 is a universal marker of CSCs among solid tumors, including OC (Ovarian Cancer)." (PMID 35328460, 2022).
ovarian carcinoma (continued). "ALDH1A1-induced drug resistance also seriously hampered ovarian cancer and leukemia treatment." (PMID 35814382, 2022). "Recent studies demonstrated that Nuclear factor E2-related factor 2 (Nrf2) activation is involved in cancer stem cell-like properties’ exposure to high ALDH1A1 concentrations that result in shorter overall survival (OS) and progression-free survival in ovarian cancer patients." (PMID 35280765, 2022). "Additionally, ALDH1A1 has been shown to contribute to PARP inhibitor resistance in ovarian cancer, and ALDH1A1 inhibition synergizes with the PARP inhibitor olaparib in killing BRAC2-mutated ovarian cancer cells." (PMID 35884498, 2022). "Furthermore, the broad analysis of multiple ovarian cancer cell lines revealed significantly higher ALDH1A1 expression and activity in taxane- and platinum-resistant cell lines." (PMID 35328460, 2022). "However, these cells can become re-sensitized to chemotherapy by ALDH1A1 silencing using nanoliposomal siRNA in ovarian cancer cell line SKOV3TRip2 and A2780cp20." (PMID 35448203, 2022). "Collectively, our data demonstrate that the inhibition of ALDH1A1 with a small-molecule inhibitor in combination with chemotherapy could suppress senescence and stemness to improve outcomes for ovarian cancer patients." (PMID 35884498, 2022). "The ALDH1A1-positive cell population was observed in drug-resistant ovarian cancers and cell lines." (PMID 35328460, 2022). "Moreover, a previous study found that ALDH1A1-silencing sensitized ovarian cancer cells to chemotherapy." (PMID 33042843, 2020). "Moreover, silencing of ALDH1A1 using nano-liposomal siRNA sensitized both taxane-and platinum resistant cell lines to chemotherapy in ovarian cancer." (PMID 33339129, 2020). "Collectively, our results consolidate the concept that ALDH1A1 plays an important role regulating stemness in ovarian cancer, describe the activity of a novel inhibitor targeting this rare and resistant cell population, and support continued efforts to optimize this new class of anti-cancer agents." (PMID 30965686, 2019). "The expression of LOX, collagens, and ALDH1A1 was also detected in ovarian cancer lesions." (PMID 30583585, 2018). "In fact, these authors have shown that primary ovarian cancer specimens were composed of low densities of cells displaying cancer stem cell markers such as ALDH1A1, CD44 and CD133; tumors collected immediately after primary therapy were more densely composed of each of these markers." (PMID 29389895, 2018). "However, due to the extremely low abundance of ALDH+ cells in the 2008 ovarian cancer cell line, we were unable to detect the ALDH1A1 protein level using immunoblotting." (PMID 29752431, 2018). "Furthermore, we demonstrated that ATRA treatment suppressed the ALDH1A1-p62 axis, and thereby inhibited NRF2 activation, resulting in the attenuation of CSC-like properties only in ALDH1-high ovarian cancer cells." (PMID 30166520, 2018). "As a result, it is suggested that ALDH1A1 could be potential therapeutic target because a small-molecule ALDH1A1 inhibitor abolished sphere formation in ovarian cancer." (PMID 29552329, 2018). "The “anti-lncRNA” agent decreased ALDH1A1 activity in ALDH(+) ovarian cancer cells, suggesting HOTAIR inhibition with PNA could reduce the ovarian cancer stem cell population." (PMID 28420874, 2017). "ALDH1A1 plays a key role in the maintenance of ovarian cancer stem cell-like properties and might mediate carboplatin resistance through altered regulation of the cell cycle and DNA repair networks." (PMID 26783961, 2016). "Since curcumin is a potent inhibitor of the ovarian cancer sphere formation, we performed western blot analysis to determine whether curcumin can modulate ALDH1A1 expression in ovarian cancer spheroids." (PMID 27863439, 2016).